SOST (sclerostin)
Diseases named in the same sentence as SOST in open-access papers (continued):
Sharing a sentence is not in itself a finding about the gene and the disease.
sarcopenia (18 papers, 2020 to 2026). Progressive decline in muscle mass due to aging which results in decreased functional capacity of muscles. "This research design addresses a specific gap in the current literature by clarifying the link between sarcopenia-related muscle weakness and circulating sclerostin within a high-risk, postmenopausal population." (PMID 41594249, 2026). "By focusing solely on older women—including those with pronounced sarcopenia—this study minimizes the influence of age-related variability and provides a more targeted assessment of how muscle loss is associated with sclerostin concentrations." (PMID 41594249, 2026). "Our study demonstrated that circulating sclerostin levels are more closely associated with muscle strength than muscle mass, suggesting its function as a potential biomarker for monitoring muscle function in individuals with sarcopenia." (PMID 41594249, 2026). "In addition, abnormal values of some serum/plasma parameters were suggested as possible markers of muscle loss and possibly sarcopenia, such as the creatinine to cystatin C ratio, irisin, sclerostin, and brain natriuretic peptide." (PMID 35565832, 2022). "Consequently, reduced physical activity associated with muscle weakness or sarcopenia may result in elevated sclerostin levels and impaired bone metabolism." (PMID 41594249, 2026). "As physical activity declines in aging individuals with sarcopenia, this reduced loading likely contributes to elevated sclerostin levels, impairing bone remodeling and exacerbating musculoskeletal decline." (PMID 41594249, 2026). "Future research should aim to investigate longitudinal changes in sclerostin levels with aging and their temporal relationship with the progression of sarcopenia, incorporating physical activity metrics and stratified analysis by comorbidity profiles." (PMID 41594249, 2026). "Serum sclerostin levels were significantly elevated in the sarcopenia group (158 ± 52.4 vs. 126 ± 75.7 pg/mL, p = 0.036), and regarding BMD, no significant group differences were observed for most regions." (PMID 41594249, 2026). "When applying an ROC-derived cutoff value (serum sclerostin ≥ 124.6 pg/mL), individuals with higher sclerostin levels showed significantly increased odds of sarcopenia (OR = 5.39)." (PMID 41594249, 2026). "A population study conducted in Korea involving aged adults elucidated that the elevated level of sclerostin in the samples of patients suggests a lower chance to be affected by sarcopenia and lower muscle mass." (PMID 37815907, 2024). "The sclerostin molecule, derived from the osteocytes, is considered a putative myokine involved in sarcopenia." (PMID 37815907, 2024). "In our analysis, sclerostin levels were significantly elevated in individuals with sarcopenia." (PMID 41594249, 2026). "In our study, while body weight did not significantly correlate with sclerostin, it was independently associated with sarcopenia." (PMID 41594249, 2026). "This suggests its participation in bone–muscle endocrine crosstalk, particularly relevant in sarcopenia, where impaired muscle-derived mechanical and biochemical signals may influence sclerostin-mediated bone remodeling." (PMID 41594249, 2026). "Given that sarcopenia leads to reduced physical activity, it could secondarily increase the expression of sclerostin, potentially affecting both bone and muscle." (PMID 41594249, 2026). "SOST may play a significant role in bone and muscle crosstalk by the Wnt/β-catenin signalling pathway, leading to muscle wasting and sarcopenia." (PMID 39919333, 2025). "Therefore, it is being argued that sclerostin has great potential to directly implicate sarcopenia and other metabolic implications." (PMID 36362238, 2022). "In this study, serum sclerostin levels were not measured; however, higher sclerostin concentrations, which are known to be associated with sarcopenia, may be indirectly related to the elevated TRACP-5b levels observed in our participants." (PMID 40943733, 2025).
sarcopenia (continued). "Thus, although some discrepancy exists, it seems that, overall, raised sclerostin levels may be involved in sarcopenia, something that was also observed in the alcoholic cirrhotics included in this study." (PMID 35807755, 2022). "Sclerostin is an inhibitor of this pathway and may be involved in sarcopenia." (PMID 35807755, 2022). "Therefore, sclerostin may be a potential new biomarker for sarcopenia." (PMID 36362238, 2022). "The comparative analysis of subgroups with or without DM showed only the higher mean concentration of sclerostin among DM patients, without a significant difference in the incidence of sarcopenia." (PMID 35057428, 2022).
myocardial infarction (17 papers, 2021 to 2025). Gross necrosis of the myocardium, as a result of interruption of the blood supply to the area, as in coronary thrombosis. "More importantly, when selecting instruments from random-effects meta-analysed dataset, results suggested a causal relationship between lower levels of sclerostin and lower levels of apolipoprotein-A, and an increased risk of myocardial infarction." (PMID 39537602, 2024). "A recent large GWAS of osteoporotic patients treated with romosozumab to reduce serum sclerostin levels suggests increased risk for myocardial infarction (OR 1.35 [95% CI 1.01–1.79])." (PMID 38791593, 2024). "Our analyses provide evidence of a causal relationship between reduced sclerostin and an increased risk of coronary artery disease and myocardial infarction." (PMID 39537602, 2024). "Two out of three Mendelian randomisation studies provided further evidence for increased cardiovascular risk, with those genetically predisposed to lower sclerostin found to be at increased risk of myocardial infarction and T2D and one study finding greater coronary arterial calcification." (PMID 38093031, 2024). "However, random-effects results showed an association between lower levels of sclerostin and decreased levels of apolipoprotein-A (beta = −0.22 [−0.38, −0.07]), and with increased risk of myocardial infarction (OR = 2.67 [1.16, 6.1]; HR = 2.62 [1.17, 5.84])." (PMID 39537602, 2024). "One study found higher serum levels of SOST in myocardial infarction patients who developed cardiac remodeling after one year, suggesting that SOST may play a key role in the development of vascular remodeling." (PMID 40563496, 2025). "For example, the potential SOST target, ANXA2, plays a role in protective vascularization following myocardial infarction, interacting with macrophage YAP and integrin signaling as well as PI3K/AKT signaling." (PMID 39430425, 2024).
prostate carcinoma (17 papers, 2013 to 2025). A carcinoma that arises from epithelial cells of the prostate gland. "Sclerostin, by restricting the Wnt-signaling pathway, inhibited prostate cancer migration and sclerostin deficiency resulted in increased prostate-cancer spread." (PMID 35160258, 2022). "The implication of sclerostin in the biology of bone loss in bone disorders and in malignant diseases like breast or prostate cancer has attracted research interest in this direction." (PMID 32640686, 2020). "In prostate cancer, which typically forms osteoblastic lesions characterized by high bone formation, the levels of sclerostin, or DKK-1, can vary during disease progression, adding complexity to our understanding of the role of osteocytes in this process." (PMID 37174109, 2023). "It has been reported that Wnt hyperactivity is limited in prostate cancer, but the expression of the Wnt antagonist sclerostin is also low." (PMID 37840014, 2023). "In in vitro models, conditioned media from prostate cancer cells decreases the expression of sclerostin and DKK-1 in osteocytes." (PMID 37174109, 2023). "In patients with prostate cancer, sclerostin levels were lower than in patients with benign prostatic hyperplasia." (PMID 35160258, 2022). "PC3 prostate cancer cells which overexpressed the SOST gene showed less osteolysis when injected into the femur of non-obese diabetic (NOD) scid gamma (NSG) mice and significantly less metastases when administered intravenously." (PMID 35160258, 2022). "It has been reported that in some disease states, in which osteoblast number or osteoblastic activity is increased, such as Paget’s disease of bone and prostate cancer, sclerostin levels were found to correlate with the rate of bone turnover." (PMID 32640686, 2020). "Once released, sclerostin inhibits osteoblast function; in prostate cancer, which predominantly produces osteoblastic bone metastases, sclerostin levels are low." (PMID 32640686, 2020). "Sclerostin levels are significantly elevated in patients with prostate cancer." (PMID 39747949, 2025). "Aimy Sebastian investigated an in vitro co-culture model of PC3 prostate cancer cells and osteoblasts and found that reduced SOST expression in the tumor microenvironment may promote bone metastasis in prostate cancer through up-regulation of MALAT1." (PMID 38172792, 2024). "The concept of sclerostin inhibition may be especially promising in patients with prostate cancer, as elevated levels of sclerostin have been reported in med with prostate cancer receiving ADT." (PMID 25802521, 2015). "Concerning osteocyte involvement into prostate cancer progression in bone, we found that the expression of SOST, an inhibitor of Wnt signaling, was induced by PC3 cells conditioned medium, suggesting a direct effect of osteocytes on OB differentiation during tumor bone progression." (PMID 24069383, 2013). "Low sclerostin and noggin levels in combination with high BMP6 expression had a predictive value for prostate cancer progression and metastases." (PMID 35160258, 2022). "They found that osteocytes modify their phenotype and show decreased expression of sclerostin and increased levels of DKK-1 in the presence of conditionally reprogrammed primary human prostate cancer cells." (PMID 32640686, 2020). "In order to characterize ongoing bone cell activity in clinical cases of prostate cancer bone metastasis, we selected a set of genes to represent osteoclast activity (ACP5, CTSK, MMP9), osteoblast activity (ALPL, BGLAP, RUNX2) and osteocytes (SOST)." (PMID 29670000, 2018). "Inhibitors of Wnt signaling have been shown to be involved in prostate cancer (PC) metastasis; however the role of Sclerostin (Sost) has not yet been explored." (PMID 26545120, 2015). "Sclerostin overexpression, but not DKK-1 overexpression, in prostate cancer cells decreased metastasis and migration of prostate cells." (PMID 37174109, 2023).
metabolic syndrome (13 papers, 2020 to 2026). A cluster of metabolic risk factors for CARDIOVASCULAR DISEASES and TYPE 2 DIABETES MELLITUS. "Further, sclerostin was negatively associated with the ankle-brachial index, renal function, and dyslipidemia markers." (PMID 40731833, 2025). "Circulating sclerostin in humans is associated with metabolic syndrome, as was also observed in our experiment." (PMID 34945658, 2021). "Previous studies found increased sclerostin levels in type 2 diabetic patients compared with age-matched controls and type 1 diabetic patients, and sclerostin increased with the number of metabolic syndrome features." (PMID 34421825, 2021). "In vivo models using ovariectomised or metabolic syndrome rats demonstrated that TT supplementation modulated key osteocyte-secreted factors, including sclerostin, dentin matrix protein 1, Dickkopf-related protein 1, fibroblast growth factor 23, and receptor activator of nuclear factor κB ligand." (PMID 41800088, 2026). "In rats with metabolic syndrome, AT lowered RANKL, SOST, DKK-1 and fibroblast growth factor-23 level." (PMID 34790038, 2021). "Both tocotrienols also prevented the increase in sclerostin and DKK-1 levels in the animals with metabolic syndrome, which negatively regulate the activation of Wnt/β-catenin by preventing the binding of Wnt ligands to the frizzled receptor, lipoprotein receptor-related protein 5/6." (PMID 36144598, 2022). "In addition, sclerostin levels were not different between subjects with or without dyslipidemia (data not shown)." (PMID 34572220, 2021). "In addition, the negative correlation between sclerostin and HDL-C levels points toward a connection with dyslipidemia." (PMID 40731833, 2025).
renal failure (13 papers, 2012 to 2025). "The obtained results confirm prior observations of increased blood levels of FGF-23 and sclerostin in patients with renal insufficiency." (PMID 36970967, 2023). "Elevated serum levels of FGF-23 and sclerostin are seen along with higher bone expressions in renal insufficiency." (PMID 36970967, 2023). "SOST is an inhibitor of bone formation derived from osteocytes and is increased in cases of kidney failure, particularly in CKD patients with VC." (PMID 38249346, 2023). "This explanation appears to have a strong basis, in view of the fact that sclerostin levels have been shown to be increased in both patients with acute kidney injury and patients with chronic kidney dysfunction." (PMID 37371669, 2023). "Sclerostin was also significantly higher in patients with stage 3 renal insufficiency (mean, 0.832 ± 0.096 ng/mL) compared to those with stage 1 disease (0.593 ± 0.035 ng/mL; Mann-Whitney, p = 0.022)." (PMID 31881044, 2019). "In non-dialysis CKD, observational studies show that serum levels of Sclerostin increase along with the stages of renal failure and correlate positively with serum FGF23 and phosphate." (PMID 28558021, 2017). "Literature data report higher levels of sclerostin in patients with renal insufficiency." (PMID 37371669, 2023). "An important advantage of the present study design was the exclusion of diseases and drugs that may interfere in bone metabolism since kidney failure, hyperparathyroidism and bisphosphonates could regulate sclerostin expression in osteocytes and consequently affect the sclerostin serum levels." (PMID 23062122, 2012). "During in vivo models of acute kidney injury and CKD vascular (aortic) expression of sclerostin was also increased." (PMID 39078512, 2024). "In another study, sclerostin was negatively correlated with bone mineral density in men and women without renal failure and with the size of the calcified vascular plaques." (PMID 40636828, 2025). "Our findings demonstrate that TGF-β1 may participate in phosphate-induced vascular calcification and renal failure, probably by promoting the Wnt/β-catenin signaling through COX-2 to repress sclerostin." (PMID 33159018, 2020). "One possibility is that renal failure leads to skeletal resistance to PTH, and decreases in PTH signalling activity might result in increased production of sclerostin in CKD patients." (PMID 25053944, 2014). "Our study investigated the negative effects of renal failure and its relationship with phosphorus, FGF23, PTH, sclerostin, and bone." (PMID 29394885, 2018).
type 1 diabetes (13 papers, 2017 to 2025). "Sclerostin was negatively associated with C-peptide and HbA1c in children with type 1 diabetes implying an interaction between sclerostin and glucose metabolism." (PMID 35563144, 2022). "SOST-gene expression is increased by glucose and glycation end products as well as in mice with diabetes type 1, while androgens and estrogens suppress SOST-gene expression." (PMID 35160258, 2022). "Previous studies reported a positive correlation between sclerostin and osteocalcin levels in children with type 1 diabetes and in obese children and adolescents." (PMID 34572220, 2021). "Interestingly, the proportion of sclerostin-positive osteocytes in the DPS group was lower than the DP group, suggesting that SIM may improve bone formation in type 1 diabetes by inhibiting sclerostin expression in osteocytes." (PMID 30413166, 2018). "Associations between skin AGEs and BMD, trabecular bone score, bone turnover markers, and sclerostin in pooled participants with and without type 1 diabetes." (PMID 38505219, 2024). "In a small cohort of girls with type 1 diabetes (T1DM), a negative association between serum sclerostin levels and glycated hemoglobin (HbA1c) was found." (PMID 32265831, 2020). "Additionally, serum sclerostin levels are higher in type 1 diabetes mice than those in normal mice." (PMID 29240821, 2017).
ankylosing spondylitis (12 papers, 2012 to 2025). An autoimmune chronic inflammatory disorder characterized by inflammation in the vertebral joints of the spine and sacroiliac joints. "Sclerostin in serum as well as in bone tissue from joints analyzed by immunohistochemistry was lower in patients with ankylosing spondylitis." (PMID 41326868, 2025). "In mice with ankylosing spondylitis, sclerostin autoantibodies were detected, suggesting their possible contribution to its pathogenesis." (PMID 35160258, 2022). "This reduction in sclerostin levels was more pronounced in patients with ankylosing spondylitis who already developed syndesmophytes than in patients who did not." (PMID 35160258, 2022). "In this report we have tested the effects of treatment with recombinant SOST to reduce osteoproliferation in the proteoglycan-induced spondylitis (PGISp) mouse model of ankylosing spondylitis." (PMID 26612313, 2015). "Similarly, serum sclerostin levels in patients with ankylosing spondylitis were significantly lower than controls." (PMID 35160258, 2022). "Therefore, sclerostin levels could be used as a biomarker for the prediction of syndesmophyte formation in ankylosing spondylitis." (PMID 35160258, 2022). "While in control samples, about 30% of the osteocytes were negative for sclerostin, in patients with ankylosing spondylitis, these were nearly 80% of the osteocytes without any increase in percentage of empty lacunae." (PMID 41326868, 2025). "So far, the role of the Wnt/β-catenin pathway and its inhibitors (Dickkopf and sclerostin) has been evaluated in ankylosing spondylitis (AS), but in PsA has not been studied sufficiently." (PMID 32676565, 2020). "Similarly, Wnt signaling inhibitors sclerostin and DKK-1 have been investigated as biomarkers for disease activity in ankylosing spondylitis (AS), and a lower level of serum DKK-1 was observed in AS patients." (PMID 28373995, 2017). "Sclerostin levels have been reported to be low in ankylosing spondylitis (AS), but there is no data regarding the possible role of this Wnt inhibitor during anti-tumor necrosis factor (TNF) therapy." (PMID 23062122, 2012).